MOG (myelin oligodendrocyte glycoprotein)
Diseases named in the same sentence as MOG in open-access papers (continued):
Sharing a sentence is not in itself a finding about the gene and the disease.
experimental autoimmune encephalomyelitis (continued). "Axonal and neuronal pathologies are a central constituent of multiple sclerosis (MS) and its animal model, experimental autoimmune encephalomyelitis (EAE), induced by the myelin oligodendrocyte glycoprotein (MOG) 35–55 peptide." (PMID 34948217, 2021). "While the etiology is not well understood in humans, myelin oligodendrocyte glycoprotein and proteolipid protein peptides (MOG and PLP, respectively) induce experimental autoimmune encephalomyelitis (EAE) in mice, a model used extensively to study MS." (PMID 34298921, 2021). "CLIC1−/− BMDC displayed reduced in vitro antigen processing and presentation of full-length myelin oligodendrocyte glycoprotein (MOG) and reduced MOG-induced experimental autoimmune encephalomyelitis." (PMID 27113959, 2016). "These Ncf1 knockout mice were also reported to be completely protected from experimental autoimmune encephalomyelitis (EAE), when the disease was induced by the myelin oligodendrocyte glycoprotein (MOG) peptide." (PMID 26528554, 2015). "One of the most commonly used animal models of multiple sclerosis is experimental autoimmune encephalomyelitis (EAE), which is induced by immunization with myelin oligodendrocyte glycoprotein (MOG)." (PMID 24592383, 2014). "MOG has been the subject of intense research in MS and the experimental autoimmune encephalomyelitis (EAE) model of MS over the last 10 years or so, and there are numerous publications on the topic of autoimmune reactivity to MOG protein and peptides." (PMID 24312732, 2013). "BTN inhibits the MOG-induced experimental autoimmune encephalomyelitis (EAE), but also induces inflammatory responses in the CNS, when injected alone into animals, and stimulates in vitro MOG-specific T cell responses." (PMID 21461338, 2011). "Experimental autoimmune encephalomyelitis (EAE), in which mice are immunized with the encephalitogenic myelin oligodendrocyte glycoprotein (MOG) peptide, is used as a model of MS." (PMID 22135673, 2011). "An autoimmune model of MS, experimental autoimmune encephalomyelitis (EAE), has also supported the autoimmune theory, where EAE can be induced by sensitization with CNS antigens, including myelin oligodendrocyte glycoprotein (MOG) and myelin proteolipid protein (PLP)." (PMID 40558498, 2025). "According to this, particularly noteworthy are the findings from an in vivo study on mice with experimental autoimmune encephalomyelitis (EAE), an animal model of MS, induced by auto-immunization with myelin oligodendrocyte glycoprotein (MOG) and BBB disruption via pertussis toxin." (PMID 40332285, 2025). "The experimental autoimmune encephalomyelitis (EAE) model, induced by immunizing animals with myelin-derived proteins (or polypeptides), such as myelin oligodendrocyte glycoprotein (MOG), proteolipid protein (PLP), and myelin basic protein (MBP), serves as a classic animal model of MS." (PMID 38243312, 2024). "A frequently used and well-validated animal model of MS is the experimental autoimmune encephalomyelitis (EAE) mouse model, in which the autoimmune disease is induced by active immunization with an encephalitogenic peptide (e.g., MOG35–55) from the myelin oligodendrocyte glycoprotein (MOG)." (PMID 36675155, 2023). "Recently, Yi and colleagues reported that CD8+ T cells expressing a myelin oligodendrocyte glycoprotein (MOG) peptide–MHCII CAR construct can efficiently deplete higher-affinity peptide-specific CD4+ T cells in vivo and prevent initiation of experimental autoimmune encephalomyelitis (EAE)." (PMID 37731505, 2023). "In experimental autoimmune encephalomyelitis (EAE) an external immunization step is required to induce sensitization of myelin antigens, such as myelin oligodendrocyte glycoprotein (MOG), using an adjuvant that usually comprises of bacterial components to activate the immune system." (PMID 37904733, 2023).
experimental autoimmune encephalomyelitis (continued). "Experimental autoimmune encephalomyelitis induced by immunization of non-obese diabetic (NOD) mice with MOG 35–55 peptide has been described as having relapses with worsening disability." (PMID 36340686, 2022). "In experimental autoimmune encephalomyelitis (EAE), a widely used experimental mouse model for MS, the auto-immune aspect of MS is mimicked by inducing an immune response against the myelin oligodendrocyte glycoprotein (MOG)." (PMID 36120103, 2022). "In the field of autoimmune demyelinating diseases, visual impairments have extensively been studied using the experimental autoimmune encephalomyelitis (EAE) mouse model, which is classically induced by immunization with myelin oligodendrocyte glycoprotein peptide (MOG35–55)." (PMID 35197067, 2022). "The most common experimental animal model for this disease is experimental autoimmune encephalomyelitis (EAE), which is induced by immunization with CNS tissue or myelin peptides, such as MOG, myelin basic protein (MBP), and proteolipid protein (PLP) in complete Freund’s adjuvant (CFA)." (PMID 35743229, 2022). "Therefore, we induced a commonly used mouse model of multiple sclerosis, experimental autoimmune encephalomyelitis (EAE), by immunizing mice with the myelin oligodendrocyte glycoprotein (MOG)." (PMID 35169263, 2022). "Here, we report genetic engineering of hematopoietic stem cells (HSCs) to express myelin oligodendrocyte glycoprotein (MOG), specifically in platelets, as a means of intervention to induce immune tolerance in experimental autoimmune encephalomyelitis (EAE), the mouse model of MS." (PMID 36389708, 2022). "Experimental autoimmune encephalomyelitis (EAE) induced by injection of antibodies against myelin oligodendrocyte glycoprotein (MOG) is reduced in knockout mice lacking IFNAR." (PMID 36430870, 2022). "Recently, CAR Tregs were developed to treat an experimental autoimmune encephalomyelitis (EAE) mouse model of multiple sclerosis (MS), with an scFv targeting the myelin oligodendrocyte glycoprotein (MOG) protein, a key protein that is attacked, leading to myelin degradation." (PMID 35884798, 2022). "RTL551, which contains the α1 and β1 domains of the I-A(b) class II molecule covalently linked to the encephalitogenic MOG-35-55 peptide, reversed symptoms in experimental autoimmune encephalomyelitis mice and reduced IL-17 and TNF-α secretion from MOG-33-35 reactive CD4+ T cells." (PMID 34335623, 2021). "The most commonly used model of CNS autoimmunity is experimental autoimmune encephalomyelitis (EAE): induction of cerebral and spinal inflammation by myelin autoantigens, such as myelin oligodendrocyte glycoprotein (MOG), proteolipid protein (PLP) and myelin basic protein (MBP)." (PMID 33108502, 2021). "Although the biological function of MOG has not been explained thoroughly, it has already been used to induce a variety of experimental models, such as experimental autoimmune encephalomyelitis (EAE), which confirms its encephalitogenic property." (PMID 34691028, 2021). "Experimental autoimmune encephalomyelitis (EAE) is an animal model of brain inflammation, where autoreactive T and B cells to neuro-antigens, such as myelin basic protein and myelin oligodendrocyte glycoprotein (MOG), play a major role." (PMID 32210952, 2020). "To determine the roles of TIPE2 and TNFAIP8 in experimental autoimmune encephalomyelitis (EAE), an animal model for MS, we immunized WT, Tipe2–/–, Tnfaip8–/–, and Tipe2–/–Tnfaip8–/–DKO mice with myelin oligodendrocyte glycoprotein (MOG) peptide 35–55, and monitored daily for clinical signs of EAE." (PMID 32313148, 2020). "Adoptive transfer experimental autoimmune encephalomyelitis (EAE), in which myelin oligodendrocyte glycoprotein (MOG)-specific T cells are differentiated in vitro and subsequently transferred to recipient mice to induce EAE, is a common animal model to investigate T cell-driven neuroinflammation." (PMID 33243290, 2020).
experimental autoimmune encephalomyelitis (continued). "Moreover, Rg3 alleviated the onset and severity of experimental autoimmune encephalomyelitis (EAE), induced by transferring myelin oligodendrocyte glycoprotein (MOG)-reactive T cells." (PMID 31936879, 2020). "To address the implications of Gsta4 over-expression in a model of autoimmune demyelination we induced experimental autoimmune encephalomyelitis (EAE) in DAWt and DAGsta4 rats by sub-cutaneous injection of recombinant myelin oligodendrocyte glycoprotein (MOG) in adjuvant." (PMID 32792491, 2020). "Experimental autoimmune encephalomyelitis (EAE) can be induced by sensitization with CNS antigens, including myelin basic protein (MBP), myelin proteolipid protein (PLP), and myelin oligodendrocyte glycoprotein (MOG)." (PMID 30941144, 2019). "Then, it was shown that the monoclonal MOG-specific Ab 8–18C5 induces demyelination in Lewis (LEW) rats with experimental autoimmune encephalomyelitis (EAE), that guinea pigs immunized with M2 show demyelinated lesions in their CNS, and that the M2 protein is identical to MOG." (PMID 28533781, 2017). "Development of MOG-induced experimental autoimmune encephalomyelitis is not dependent on Arg, but Arg plays a role for the number of B cells in immunized mice." (PMID 34527426, 2016). "To study the effects of the TSPO ligand etifoxine on neuroinflammatory damage, we used experimental autoimmune encephalomyelitis (EAE), a model of MS in mice in which an autoimmune response was induced against the myelin oligodendrocyte glycoprotein (MOG) peptide (aa 35–55)." (PMID 23681668, 2013). "Initial preclinical studies demonstrated that CAR Tregs targeting HLA-A2, factor VIII, or myelin oligodendrocyte glycoprotein (MOG) could suppress alloimmunity, autoimmunity against factor VIII in hemophilia, or experimental autoimmune encephalomyelitis, respectively." (PMID 41246323, 2025). "This approach led to disease amelioration in murine experimental autoimmune encephalomyelitis exacerbated by the administration of patient-derived myelin oligodendrocyte glycoprotein-specific antibodies, without affecting antibodies with other antigen specificities." (PMID 38390873, 2024). "Furthermore, in vitro and animal studies have shown that anti-pHERV-W antibodies recognize myelin oligodendrocyte glycoprotein and that immunization with pHERV-W, when combined with the MOG35–55 peptide, can activate experimental autoimmune encephalomyelitis (EAE)." (PMID 39850873, 2024). "Experimental autoimmune encephalomyelitis (EAE) is the most used and validated animal model for MS, where an injection with a known antigen against the myelin sheath, usually myelin oligodendrocyte glycoprotein (MOG) along with an adjuvant induces an autoimmune response." (PMID 36501116, 2022). "In an experimental autoimmune encephalomyelitis (EAE) rat model, intraperitoneal injection of EPO (5000 U/kg) significantly increased the survivability and functionality of RGCs in rats afflicted with myelin oligodendrocyte glycoprotein (MOG)-induced optic neuritis." (PMID 35806148, 2022). "Thus, we next tested whether Rg3 can ameliorate the severity of experimental autoimmune encephalomyelitis (EAE) in a mouse disease model for MS, induced by a transfer of MOG-reactive Th17 cells." (PMID 31936879, 2020). "For example, in the experimental autoimmune encephalomyelitis (EAE) model, some investigators have reported that IL-33 blockade during the developing stage of MOG-induced EAE reduces the severity of the disease, in part, due to the inhibition of MOG-dependent IL-17 and IFN-γ production." (PMID 26082774, 2015). "Surprisingly, intravenously injected NSCs displayed no significant therapeutic impact on clinical and pathological disease outcomes in mice with experimental autoimmune encephalomyelitis (EAE) induced by recombinant myelin oligodendrocyte glycoprotein, independent of the cell source." (PMID 22514711, 2012).
experimental autoimmune encephalomyelitis (continued). "Purified IgG2a monoclonal anti-MOG antibody and mouse complement were stereotactically injected into the corpus callosum of wild-type and type I IFN receptor deficient mice (IFNAR1-KO) with and without pre-established experimental autoimmune encephalomyelitis (EAE)." (PMID 28646890, 2017). "Experimental autoimmune encephalomyelitis (EAE) prone C57BL/6 (T- and B-lymphocyte response), non-autoimmune CBA, and Th mice with T cell response were immunized with myelin oligodendrocyte glycoprotein (MOG35–55) to compare different characteristics of autoimmune reaction development." (PMID 31905713, 2019). "In a transgenic mouse model, constitutive production of Ab against myelin oligodendrocyte glycoprotein (MOG) was sufficient to promote spontaneous experimental autoimmune encephalomyelitis (EAE) in the absence of B cells, when mice endogenously contained MOG-recognizing T cells." (PMID 27022743, 2016). "Interestingly, antigen-nonspecific T cells, including myelin oligodendrocyte glycoprotein (MOG) tetramer–negative CD4+ Th17 cells, also infiltrate the central nervous system (CNS) in significant proportions and exacerbate experimental autoimmune encephalomyelitis (EAE) pathogenesis." (PMID 37121980, 2023).
multiple sclerosis (364 papers, 2005 to 2026). A progressive autoimmune disorder affecting the central nervous system resulting in demyelination. "Central vein sign (CVS) is a common feature in multiple sclerosis (MS) lesions, but its frequency in myelin oligodendrocyte glycoprotein antibody-associated disease (MOGAD) varies significantly across studies." (PMID 41512208, 2026). "In clinical validation studies, patients with AQP4-IgG positive NMOSD, multiple sclerosis, or myelin oligodendrocyte glycoprotein antibody-associated disorder and healthy individuals were tested." (PMID 39941228, 2025). "Demyelinating diseases such as multiple sclerosis or MOG antibody associated disease (MOGAD) are another well-known mimic of neurosarcoidosis." (PMID 41328180, 2025). "Other acute demyelinating diseases like neuromyelitis optica (NMO), multiple sclerosis (MS), and myelin oligodendrocyte glycoprotein (MOG)-related disorders have also been reported as a cause." (PMID 40135036, 2025). "Differential diagnosis: the differential diagnosis for NMOSD includes multiple sclerosis (MS) and myelin oligodendrocyte glycoprotein (MOG)-antibody-associated diseases." (PMID 40687165, 2025). "In multiple sclerosis patients, bilateral thalamic atrophy was observed, whereas patients with myelin oligodendrocyte glycoprotein antibody‐associated disease showed atrophy of the bilateral fornix and stria terminalis." (PMID 41254968, 2025). "Myelin oligodendrocyte glycoprotein antibody‐associated disease (MOGAD) has emerged as an acquired immune‐mediated demyelinating disorder of the central nervous system distinct from multiple sclerosis (MS)." (PMID 40105307, 2025). "On the other hand, antibody cross-reactivity between Btn1a1 and Myelin Oligodendrocyte Glycoprotein is implicated in Multiple Sclerosis 27,28." (PMID 40791429, 2025). "AQP4-IgG is highly useful for differentiating NMOSD from other inflammatory diseases of the CNS, such as multiple sclerosis (MS) and myelin oligodendrocyte glycoprotein antibody-associated disease (MOGAD)." (PMID 39941228, 2025). "Demyelination disrupts the transmission of electrical signals in the brain and affects neurodevelopment in children with disorders such as multiple sclerosis and myelin oligodendrocyte glycoprotein-associated disorders." (PMID 39534724, 2024). "Acquired demyelinating syndromes (ADS) such as multiple sclerosis (MS) and myelin oligodendrocyte glycoprotein antibody disease (MOGAD) often cause cognitive impairment and fatigue in children and adults." (PMID 39359055, 2024). "Pain often precedes vision change, and is characteristic of Multiple Sclerosis (MS)-associated ON, and ON associated with anti-myelin oligodendrocyte glycoprotein antibodies (MOG-ON) and anti-aquaportin-4 antibodies (AQP4-ON)." (PMID 38867071, 2024). "Diagnosis of NMOSD is based on International consensus diagnostic criteria within the exclusion of common differentials such as multiple sclerosis and myelin oligodendrocyte glycoprotein antibody‐associated disease." (PMID 37415585, 2023). "As in the experimental autoimmune encephalitis (EAE) model of multiple sclerosis, a partial sequence of the myelin oligodendrocyte glycoprotein (MOG35–55) was identified as a causative autoantigen." (PMID 37765078, 2023). "Autoimmune responses against MOG have been associated with demyelinating disorders such as multiple sclerosis." (PMID 38235150, 2023). "NMOSD, multiple sclerosis (MS), and myelin oligodendrocyte glycoprotein antibody‐associated disease (MOGAD) were our patient's main differentials." (PMID 37415585, 2023). "Multiple sclerosis (MS) and myelin-oligodendrocyte glycoprotein (MOG) antibody-associated disease (MOGAD) are two major autoimmune-inflammatory demyelinating diseases of the central nervous system (CNS) associated with optic neuritis (ON) in children." (PMID 35869995, 2022).